PTBP1 (polypyrimidine tract binding protein 1)
Diseases named in the same sentence as PTBP1 in open-access papers (continued):
Sharing a sentence is not in itself a finding about the gene and the disease.
cancer (continued). "Studies focusing on its RNA splicing regulatory role in the nucleus have found that PTBP1 may promote a malignant phenotype in cancer cells." (PMID 31729427, 2019). "Indeed studies have shown that cancer cells have an altered PTBP1 expression and the RNA splicing regulatory role of PTBP1 in the nucleus plays a role in promoting malignant phenotype in cancer cells." (PMID 31729427, 2019). "The known involvement of PTBP1 in cancer motivated us to check if inhibition of its splicing activity could inhibit transformation." (PMID 30962446, 2019). "MiR-145 could directly bind to TAGLN2 to suppress BC cell proliferation and migration and silence c-Myc to inhibit the PTBP1/PKMs Axis, thereby reducing the cancer-specific energy metabolism." (PMID 30871066, 2019). "Altered PTBP1 expression in cancer cells has been documented." (PMID 31729427, 2019). "Since PTBP1 is abundant in cancer cells we moved forward with studies focused on PTBP1 over PTBP2." (PMID 30568224, 2019). "Together, NOVA1 and PTBP1 have a role in driving the FL splicing of hTERT in cancer." (PMID 30568224, 2019). "Meanwhile, PTBP1 regulates the pro-inflammatory senescence-associated secretory phenotype by controlling the exon 7 skipping of EXOC7, thereby inducing inflammation-driven cancers." (PMID 31065692, 2019). "Importantly, PNCTR is markedly overexpressed in a variety of cancer cells and its downregulation is sufficient to induce programmed cell death at least in part by stimulating PTBP1 splicing regulation activity." (PMID 30318443, 2018). "Notably, the combination treatment not only impaired the cancer specific energy metabolism by inhibiting c-Myc/PTBP1/PKMs axis but also inactivated MAPK/ERK and PI3K/AKT pathways examined in vitro and in vivo." (PMID 28106737, 2017). "In the current study, we investigated whether the c-Myc/PTBP1/PKMs axis was crucial for the Warburg effect, in which PTBP1 is oncogenic and an important driver gene in many kinds of cancers, possibly in cancer stem cells." (PMID 28106737, 2017). "We next examined the intracellular levels of lactic acid and ATP to investigate metabolic changes as a consequence of suppression of the c-Myc/PTBP1/PKMs axis operating in the cancer specific energy metabolism and of switching PKM isoforms from PKM2 to PKM1 by each treatment." (PMID 28106737, 2017). "Western blot analysis at 72 h indicated that treatment with either agent alone reduced the expression level of PTBP1 and modulated the cancer specific energy metabolism through switching of PKM isoform expression from PKM2 to PKM1, thus resulting in a reduction in the PKM2/PKM1 ratio." (PMID 28106737, 2017). "It is known that pyruvate kinase in muscle (PKM), which is a rate-limiting glycolytic enzyme, has essential roles in the Warburg effect and that expression of cancer-dominant PKM2 is increased by polypyrimidine tract-binding protein 1 (PTBP1), which is a splicer of the PKM gene." (PMID 26980745, 2016). "Moreover, PTBP1 has been demonstrated to be essential in the regulation of cell growth and cancer cells survival." (PMID 22911749, 2012). "In addition, elevated PTBP1 levels have been shown to support aerobic glycolysis and enhance translation of hypoxia-inducible factor 1α (HIF-1α), which enables cancer cells to survive hypoxic conditions associated with altered ROS homeostasis." (PMID 22911749, 2012). "Finally, we identified RBM47 and PTBP1 as regulators of KRAS E4 alternative splicing in cancer." (PMID 41368203, 2026). "Finally, the aberrant expression of PTBP1 has been associated with a wide range of cancers, but the exact mechanisms have not been fully elucidated." (PMID 40579921, 2025). "Given the relevance of PTBP1 in many cancers, future studies could focus on developing drugs or therapeutic strategies targeting PTBP1 to modulate its function and improve tumour therapeutic efficacy, which may include small molecule inhibitors or RNA interference technologies, among others." (PMID 40579921, 2025).
cancer (continued). "However, the relationship between PTBP1 expression and gene methylation, cancer prognosis, and tumor microenvironment remains unclear." (PMID 38918441, 2024). "Surprisingly, the mRNA levels of PTBP1, together with three pluripotency factors Oct4, Nanog and Sox2 were robustly elevated in spheroid cultures than in monolayer cultures of two GC cells, which were responsible for converting cancer cells from differentiated to a stem-cell-like state." (PMID 36635500, 2023). "In addition, higher expression of PTBP1 was correlated with cancer stage and poor prognosis." (PMID 35600383, 2022). "Furthermore, RBP-transcript regulation and transcript-drug associations in cancer were combined to build RBP-transcript-drug axes, wherein PTBP1 was experimentally validated to affect the sensitivity to decitabine by regulating the expression of the KIAA1522-a6 transcript of the KIAA1522 gene." (PMID 36357395, 2022). "Various studies have reported that PTBP1 regulates oncogenic splicing switch in pyruvate kinase from splice variant PKM1 towards PKM2, thereby contributing to energy metabolism remodeling from oxidative phosphorylation to aerobic glycolysis, as well as resistance to cancer therapy." (PMID 36418319, 2022). "The decoy oligonucleotide against PTBP1 was successful in inhibiting the oncogenic properties of the cells, which opens up the possibility of treatment of cancer with these types of decoy oligonucleotides, targeting splicing factors that are upregulated in certain cancer types." (PMID 30962446, 2019). "PTBP1 was further detected due to higher expression in the circFOXP1-sense probe compared with the circFOXP1-antisense sample or no RNA sample, and previous studies have verified that PTBP1 is associated with the Warburg effect in cancer cells through regulation of the PKM1/PKM2 ratio." (PMID 31623628, 2019). "Hence, PTBP1 presents a potentially powerful therapeutic target for inflammation-driven cancer." (PMID 29990503, 2018). "Moreover, PTBP1 promotes PKM2 expression in most cancers, thus maintaining the “Warburg effect”." (PMID 30279379, 2018). "Expression of PTBP1 positively correlates with growth of various cancers and poor prognosis but had yet to be causally linked to the negative effect of inflammation on advanced cancer." (PMID 29990503, 2018). "Scatter plots of UCS cancer tissues confirmed positive correlations between PSI values of KRAS E4 and mRNA expression levels of RBM47 and PTBP1." (PMID 41368203, 2026). "Several splicing factors, like polypyrimidine tract binding protein (PTBP1), SR protein (SRSF1), and heterogeneous nuclear ribonucleo-proteins (hnRNPs), are highly expressed in cancer." (PMID 39863145, 2025). "Previous studies have proposed the molecular mechanism by which PTBP1, as an RBP, promotes cancer progression by stabilizing the mRNAs of key oncogenes in cancer cells." (PMID 41313521, 2025). "Moreover, extensive and rigorous studies conducted by other researchers have consistently shown that PTBP1 is significantly overexpressed in diverse malignancies, playing a critical role in oncogenesis by regulating the AS of multiple genes intricately involved in cancer development." (PMID 40296916, 2025). "Mechanistically, NAS1 binds to NR2F1 mRNA and promotes its translation by recruiting the RNA-binding protein PTBP1, thereby leading to NR2F1-mediated transcriptional suppression of ΔNp63, which induces EMT and promotes dormancy of cancer cells in the lungs." (PMID 39937018, 2025). "Polypyrimidine tract-binding protein 1 (PTBP1), a well-characterized RBP, promotes tumor progression in various cancers by modulating mRNA splicing, stability, and translation, with established roles in metabolic reprogramming and drug resistance." (PMID 41313521, 2025). "This study investigates the anti-cancer mechanisms of curcumin on CRC progression, focusing on PTBP1 and CDK2 as critical regulators." (PMID 40469179, 2025).
cancer (continued). "GO analysis revealed that both PTBP1 and DNMT3B‐L target genes were enriched in important cancer‐related pathways, including DNA damage respire." (PMID 39287090, 2024). "PTBP1 increases alternative splicing events of CD44 to produce CD44 v8-10, which promotes cancer cell invasion." (PMID 38785973, 2024). "Multiple lines of evidence support that PTBP1-mediated exon skipping of NDUFV3 exists in various cellular senescence models and cancer types." (PMID 39872664, 2024). "Additionally, PTBP1 may increase the repellence of cisplatin in certain types of cancer." (PMID 38993556, 2024). "These correlation data support the notion that PTBP1-mediated exon-skipping regulation of NDUFV3 is prevalent in diverse cellular senescence models and cancers." (PMID 39872664, 2024). "The three main members of the PTBP family are PTBP1, PTBP2, and PTBP3, of which PTBP3 promotes the growth and metastasis of cancer cells and also prevents the degradation of mRNAs." (PMID 37631029, 2023). "Consistent with previous studies, the RBPs PTBP1 and SRSF1 were differentially upregulated in 6 and 3 cancer types, respectively." (PMID 35654793, 2022). "For example, it has been shown that PTBP1 modulates pyruvate kinase M1/M2 (PKM1/M2) splicing, thereby inhibiting cancer-specific energy metabolism." (PMID 35600383, 2022). "Further analysis was performed to investigate the relationship between PTBP1 expression in LUAD tissues and clinicopathological characteristics of cancer." (PMID 35600383, 2022). "Existing evidence has suggested that PTBP1 upregulated pyruvate kinase 2 (PKM2), a glycolysis key enzyme, leading to a metabolic shift from oxidative phosphorylation to glycolysis in cancer cells." (PMID 36447254, 2022). "Our finding on the SON function in intron removal from the PTBP1 transcript suggests potential roles of SON in removing detained introns from many other transcripts, thereby promoting cancer cell growth." (PMID 34548489, 2021). "By regulating AS, splicing factors, such as PTBP1 and MBNL3, can function as oncogenes or pseudo‐oncogenes and promote cancer progression." (PMID 32939931, 2020). "Our findings indicate that the PKM splicers of PTBP1, hnRNPA1, and SRSF3 were involved in the maintenance of cancer-specific metabolism and also tumorigenesis." (PMID 30279379, 2018). "In the ASF-4-1 cell line as a normal cell, the expression levels of PTBP1, hnRNPA1, and SRSF3 were lower than those of all cancer cell lines tested." (PMID 30279379, 2018). "We show that one of the strRNAs, PNCTR, recruits multiple copies of PTBP1 protein to the PNC, a cancer-enriched nuclear body." (PMID 30318443, 2018). "We chose these cancer cell lines because they have been consistently studied in the BCL-2 field and were used in our initial characterization of PTBP1’s impact on MCL18." (PMID 29748555, 2018). "On the other hand, in all cancer cell lines tested and in human fibroblast ASF-4-1 cell line, PTBP1 was fairly expressed, and good expression of hnRNPA1 and SRSF3 was observed in most of the cancer cell lines." (PMID 30279379, 2018). "Earlier, we found that PTBP1, a major splicer of the PKM gene, is a gene responsible for maintenance of the cancer specific energy metabolism and that it is frequently overexpressed in clinical tumor samples." (PMID 28106737, 2017). "In cancer cells, PKM2 is favorably expressed through mechanisms mediated by MYC, HNRNPA, HNRNPA2B1, and PTBP1." (PMID 28257090, 2017).
cancer (continued). "We consider that the combination of siRNA for the driver gene PTBP1 and the miR-145 silencing of the plural genes associated with the networks related to PTBP1 expression, such as c-Myc and PI3K/AKT signaling molecules, could avoid drug resistance of various kinds of cancers." (PMID 28106737, 2017). "Polypyrimidine tract-binding protein 1 (PTBP1, also known as hnRNPI), is a member of the hnRNP family and promotes PKM2 expression in cancer cells." (PMID 26980745, 2016). "We show that many of these events are shared among different cancer types; our data also suggest that specific splicing factors, namely RBFOX2, QKI, MBNL1/2, PTBP1 and CELF2 are probably responsible for many of the alterations detected in these cancer types." (PMID 25908786, 2015). "In summary, we found that autoregulaton of SRSF3 expression involves inclusion of exon 4, which is regulated by PTBP1 and PTBP2 binding to an ESS motif, and that this regulatory process is impaired in OSCC cancer cells." (PMID 26416554, 2015). "Based on these profiles, we hypothesized that RBM47 and PTBP1 regulate the alternative splicing of KRAS E4, consistent with the positive correlations observed in TCGA cancer tissues." (PMID 41368203, 2026). "Our findings demonstrate that RBM47- and PTBP1-mediated alternative splicing of KRAS contributes to enhanced tumor progression, highlighting KRAS alternative splicing as a promising therapeutic target for cancer treatment." (PMID 41368203, 2026). "Based on the high expression of eIF4G2 and PTBP1 in cancer tissues, Feng and colleagues developed a circular RNA therapeutic that contains Human rhinovirus type 2 (HRV2) IRES to achieve selective translation in cancer cells overexpressing these factors." (PMID 41226581, 2025). "In addition, PTBP1 is recruited by the highly expressed RNA helicase MTR4 in HCC, promoting cancer metabolic reprogramming in HCC." (PMID 38302461, 2024). "Collectively, these findings illustrate that PTBP1 possesses an oncogenic function in LUAD through inhibiting senescence, and that targeting aberrant splicing mediated by PTBP1 has therapeutic potential in cancer treatment." (PMID 39057099, 2024). "With the assistance of RALY, PTBP1 can bind to the pre‐mRNA of DNMT3B and drive an oncogenic splicing switch in DNMT3B to produce DNMT3B‐L, which in turn induces promoter methylation of DUSP2, thereby increasing resistance of cancer cells to irradiation." (PMID 39287090, 2024). "While the PTBP1 knockdown results replicated our previous study in cancer cells, NOVA1 knockdown did not result in significant reduction of telomerase activity in iPSCs despite the significant reduction of NOVA1 expression level." (PMID 37531400, 2023). "Increases in PTBP1 expression have been described in cancer cells and are correlated with decreases in the production of the small non-coding RNA miRNA-124, suggesting that in PAH, miR-124/PTBP1/PKM2 promotes glycolysis, increases cell proliferation, and causes apoptosis resistance." (PMID 35269553, 2022). "Remarkably, PTBP1 on Th2 cells, PTBP2 on T helper cells and Tcm, and PTBP3 on T helper cells, Tcm, and Th2 cells may have broad positive regulatory effects in pan-cancer." (PMID 36203873, 2022). "PTBP1, PTBP2 and PTBP3 may be potential biomarkers for prognosis and immunotherapy in pan-cancer and may be novel immunotherapeutic targets." (PMID 36203873, 2022). "This study comprehensively and systematically analyzed the prognostic value, genetic variation, and signaling pathways of PTBP1, PTBP2, and PTBP3 and the correlation of PTBP expression with TILs, ICP, TMB, MSI, and drug sensitivity from a pan-cancer perspective." (PMID 36203873, 2022). "MYC is an essential molecular hub in CML pathophysiology and could actively participate in the dysregulation of PTBP1 and hnRNPA1 as well as PRMT5 and SRSF1, genes deregulated by MYC in other cancers." (PMID 36230624, 2022).
cancer (continued). "Thus, we investigated the expression, function, and immune characterization of PTBP1, PTBP2, and PTBP3 in pan-cancer." (PMID 36203873, 2022). "PTBP1 promotes the expression of the pyruvate kinase M1/2 isoform (PKM2) through alternative RNA splicing, which is expressed in proliferating cells and is crucial for establishing the “Warburg effect” in many types of cancers." (PMID 34769047, 2021). "PTBP1 is ubiquitously expressed in tissues and is overexpressed across cancer cell lines, regardless of NOVA1 expression patterns." (PMID 32531916, 2020). "In this study, we initially found that PTBP1 expression is increased in several common cancers, but it has no clear relationship with prognosis through bioinformatics analysis." (PMID 32207235, 2020). "PTBP1 and SRSF1 are two splicing factors known to be involved in cancer." (PMID 30962446, 2019). "The lack of PTBP2 along with elevated levels of PTBP1 in cancer led us to focus our efforts on PTBP1." (PMID 30568224, 2019). "Our results strongly suggest that PTBP1, hnRNPA1, and SRSF3 controlled cancer-specific energy metabolism at least in part through affecting the PKM gene expression profile via AS, which was clarified by RIP and IP assays, and that these proteins coding RNA would be targets for RNA medicine." (PMID 30279379, 2018). "We found that PTBP1 is the splicer responsible for determining the expression profiles of PKM isoforms; and its action leads to PKM2 expression predominantly in cancer cells, which enables the establishment and maintenance of the cancer-specific energy metabolism." (PMID 28106737, 2017). "PTBP1 is the critical determinant of PKM embryonic pyruvate kinase isoform 2, which universally over-expressed in cancer for promoting aerobic glycolysis and may affect drug resistance, in transformed cells." (PMID 28404950, 2017). "Therefore, we speculate that these miRs are fine tuners to regulate PTBP1 expression in vivo and that the dysregulation of these miRs induces the overexpression of PTBP1, leading to the establishment of the malignant phenotype in cancer cells such as the Warburg effect." (PMID 26980745, 2016). "Furthermore, the combination of PTBP1 with Linc‐ROR and miR‐124 can induce the resistance of cancer cells to gemcitabine (a chemotherapy drug), which may be achieved by activating survival signals or inhibiting the drug target pathway." (PMID 40579921, 2025). "In some cancer cells, PTBP1 could promote PKM splicing to PKM2 rather than PKM1, thus leading to a metabolic shift from OXPHOS to glycolysis." (PMID 36508323, 2023). "Several non-neuronal-specific miRNAs are also regulators of PTBP1 in various cancers." (PMID 34769047, 2021). "The silencing of LHFPL3-AS1 or PTBP1 could suppress, but not completely block, tumor progression, which is a universal phenomenon for RNAi-dependent cancer therapy." (PMID 33149126, 2020). "In the other four cancers, PTBP1 expression did not affect the prognosis." (PMID 32207235, 2020). "The study itself did not deal with the role of PTBP1 in cancer." (PMID 31130994, 2019). "Interestingly, SRSF1 is known to regulate a plethora of biological functions, further to splicing, within cells and is located in the middle of a self-regulatory network involving several splicing factors such as PTBP1 and SRSF3 that act as known oncoproteins in different types of cancer." (PMID 29415469, 2018). "Several important roles in cancer development have been recently found to be played by other splicing factors, such as the function of FOX2, RBM4, and CELF2 as tumour suppressors, the oncogenic effect of CELF1, or the regulation of SRSF3 splicing patterns by PTBP1 and PTBP2." (PMID 28374191, 2017).